ENSG00000293569 (novel protein)
Gene: Protein-coding gene on chromosome 14 (92,619,986 to 92,627,966, reverse strand). Ensembl gene ENSG00000293569.
Homologues: Paralogues in human: ERV3-1 (12% identical), ERVMER34-1 (11% identical), ERVV-2 (9% identical), ERVV-1 (9% identical), ERVW-1 (9% identical), ERVFRD-1 (9% identical).